LGALS3 (galectin 3)
Diseases named in the same sentence as LGALS3 in open-access papers (continued):
Sharing a sentence is not in itself a finding about the gene and the disease.
peripheral nerve injury (5 papers, 2015 to 2020). Injury to a peripheral nerve. "Based on our findings, GPNMB, ENPP3, Thbs2, and Lgals3 may play a key role in repair of SCs after peripheral nerve injury." (PMID 30186571, 2018). "Accordingly, previous findings of our group, in a model of peripheral nerve injury, showed that Galectin-3 knockout mice present earlier sciatic nerve regeneration due to a greater efficiency in the removal of myelin debris by macrophages and Schwann cells favoring an increase in WD speed." (PMID 30275822, 2018). "Galectin-3 has been recently considered as a key molecule in the neural functions and nerve regeneration, and inhibition of galectin-3 could attenuate neuropathic pain after peripheral nerve injury." (PMID 32509039, 2020). "Moreover, galectin-3 was found to be necessary for polarization of macrophages into the M2 phenotype, although no study has assessed the M1/M2 ratio after peripheral nerve injury in Gal-3 ko mice." (PMID 25918475, 2015).
Primary Sclerosing Cholangitis (5 papers, 2016 to 2025). "Anti-galectin-3, anti-prohibitin 1 and 2 autoantibody positivity in IRC and healthy and disease (primary sclerosing cholangitis (PSC)) control sera was assessed by ELISA/liquid chromatography–tandem mass spectrometry (LC-MS/MS)." (PMID 38332916, 2023).
prion disease (5 papers, 2012 to 2024). A transmissible disease that is caused by a protein that is able to induce abnormal folding of normal cellular proteins, leading to characteristic spongiform brain changes, which are associated with neuronal loss without an inflammatory response. "However, lysosomal activation was profoundly suppressed by galectin-3 deficiency, suggesting that galectin-3 plays a detrimental role in prion disease by regulating lysosomal function." (PMID 33672129, 2021). "Mok and coauthors suggested a detrimental role of Galectin-3 in prion diseases." (PMID 32455781, 2020). "A recent study additionally established the ligand Galectin 3 (Gal-3) and its receptor TREM2, which are involved in microglia activation and M1 polarization, to colocalize with Iba1+ microglia in terminal mice with different strains of prion disease." (PMID 38786054, 2024). "Early studies in mouse prion disease showed that lack of Galectin-3 attenuate this condition." (PMID 32455781, 2020). "Galectin-3 knockout mice express low levels of lysosomal activation marker (LAMP-2) and autophagy markers, suggesting that endosomal/lysosomal dysfunction in combination with reduced autophagy may contribute to the development of prion diseases." (PMID 22897917, 2012).
sarcoma (5 papers, 2011 to 2016). A usually aggressive malignant neoplasm of the soft tissue or bone. "Expression of galectin-3 is associated with sarcoma progression, invasion and metastasis." (PMID 22216245, 2011). "In sarcoma cells, galectin-3 disrupts focal adhesion plaques, inducing cell migration in an AKT-dependent manner." (PMID 27242966, 2016). "In sarcoma cells, a similar trend was observed, as sarcoma cells devoid of galectin-3 were rendered more migratory when exposed to extracellular galectin-3, in a process dependent on the phosphorylation of AKT." (PMID 27242966, 2016). "De novo expression of galectin-3 in a galectin-null sarcoma cell line decreased cell adhesion to laminin-111 and promoted their migratory capacity on the same substratum, in a carbohydrate-dependent manner." (PMID 24982845, 2014). "Sarcomas from both wild type and galectin-3−/− mice were cultured and three independent cell lines were obtained, S11 and S12 (derived from sarcomas of wild type mice) and Σ12 (derived from a galectin-3−/− sarcoma)." (PMID 22216245, 2011). "Regardless, exogenous galectin-3 led to decreased phosphorylation of FAK and loss of phosphorylated paxillin from the focal adhesion complexes, favoring sarcoma cell migration." (PMID 22216245, 2011). "We have also observed a decrease in the amount of phosphorylated paxillin upon exposure of sarcoma cells to galectin-3." (PMID 22216245, 2011). "Cell lines from methylcholanthrene-induced sarcomas from both wild type and galectin-3−/− mice were established." (PMID 22216245, 2011). "On the other hand, Σ12 were less migratory than S11 and S12 cells on laminin-111 substrata, indicating that galectin-3 modulated, at least in part, the interaction of sarcoma cells with laminin-111." (PMID 22216245, 2011). "When galectin-3 was transiently expressed in galectin-3−/− sarcoma cells, it inhibited cell adhesion and stimulated the migratory response to laminin in a carbohydrate-dependent manner." (PMID 22216245, 2011). "In order to investigate the role of galectin-3 in dysfunctional migration of sarcoma cells, sarcoma-derived cell lines from both wild type and galectin-3−/− mice were established." (PMID 22216245, 2011). "The promigratory activity of extracellular galectin-3 was inhibitable by wortmannin, implicating the activation of a PI-3 kinase dependent pathway in the galectin-3 triggered disruption of adhesion plaques, leading to sarcoma cell migration on laminin-111." (PMID 22216245, 2011). "Here we have provided evidence for the involvement of extracellular galectin-3 as a positive modulator of sarcoma cell migration on laminin-111." (PMID 22216245, 2011). "Despite the presence of similar levels of laminin-binding integrins on the cell surface, galectin-3−/− sarcoma cells were more adherent and less migratory than galectin-3+/+ sarcoma cells on laminin-111." (PMID 22216245, 2011). "Here we determined the role of extracellular galectin-3 on migration of sarcoma cells on laminin-111." (PMID 22216245, 2011). "We have also previously shown that experimental sarcomas expressed galectin-3, galectin-3 ligands and acquired the capacity of migrating onto basement membranes of muscle fibers, a commonly observed feature of locally invasive sarcomas." (PMID 22216245, 2011). "Altogether these results suggest the involvement of galectin-3 in the acquisition of the dysfunctional migration pattern of sarcoma cells on basement membrane proteins, such as laminin." (PMID 22216245, 2011). "Here we have addressed the role of galectin-3 in the adhesive and migratory properties of methylcholanthrene-induced sarcoma-derived cells from both galectin-3+/+ and galectin-3−/− mice on laminin-111 substrata." (PMID 22216245, 2011). "De novo expression of galectin-3 in a galectin-3−/− sarcoma cell line decreased its adhesion and promoted its migratory capacity on laminin-111, in a carbohydrate-dependent manner." (PMID 22216245, 2011).
sarcoma (continued). "To determine whether galectin-3 induced the activation of Rac1-dependent signaling pathways in sarcoma cells, we evaluated whether phosphorylated PAK accumulated in focal contacts upon exposure to galectin-3." (PMID 22216245, 2011). "Σ12 cells were then transiently transfected with galectin-3 in order to determine whether the migratory phenotype of galectin-3 expressing sarcoma cells could be restored." (PMID 22216245, 2011). "The migratory response of sarcoma cells to extracellular galectin-3 was dose-dependent." (PMID 22216245, 2011). "Migrating sarcoma cells presented increased phosphorylation levels of AKT and the promigratory activity of galectin-3 was inhibited by wortmannin, indicating its dependence on the activation of PI-3 kinase pathways." (PMID 22216245, 2011). "This is the case of the sarcoma cells studied herein, since exposure to galectin-3 led to a significant increase in phospho-AKT levels and wortmannin inhibited the promigratory activity of galectin-3." (PMID 22216245, 2011). "Galectin-3 does not lead to PAK phosphorylation and recruitment to focal adhesion complexes, suggesting the involvement of another signaling pathway in the migratory response of sarcoma cells to galectin-3." (PMID 22216245, 2011).
aneurysm (4 papers, 2015 to 2022). Bulging or ballooning in an area of an artery secondary to arterial wall weakening. "Nevertheless, persistent, elevated galectin-3 levels were still detected in the late convalescent phase of the disease (more than a year) and its plasma concentration was higher in children with aneurysms than in those without coronary artery involvement." (PMID 35410028, 2022). "However, the galectin-3 level was not significantly different in children with and without aneurysms in the acute phase of the disease." (PMID 35410028, 2022).
aortic valve stenosis (4 papers, 2017 to 2025). Aortic valve stenosis (AVS) is a condition characterized by narrowing of the heart's aortic valve opening. "A Web Of Science search was performed with the following structure: (TS = ((“transcatheter aortic valve replacement” OR “tavi” OR “aortic valve stenosis/surgery” OR “aortic valve stenosis/therapy” OR “aortic valve replacement”))) AND TS = (LGALS3 OR GDF-15 OR galectin 3 OR galectin-3)." (PMID 41010905, 2025).
bacteremia (4 papers, 2014 to 2023). "Among these, we found up-regulated genes encoding for inflammation and phagocytosis associated proteins (e.g., Apoe, Lgals3, Trem1, and C3), indicating a prolonged transcriptional activation of microglia for at least 20 days following bacterial sepsis." (PMID 37235660, 2023). "In addition, galectin-3 null mice demonstrated reduced levels of bacteremia, compared to wildtype mice, after challenge with live N. meningitidis, further implicating galectin-3 in promoting bacterial infection of host cells." (PMID 24995007, 2014).
cardiac arrest (4 papers, 2022 to 2025). Cessation of breathing and/or cardiac function. "Overall, our study highlights the significance of galectin-3 as a strong predictor of long-term mortality and cerebral disability in post-cardiac arrest patients." (PMID 39338248, 2024). "By linking elevated circulating galectin-3 level with increased mortality in cardiac arrest patients, our results reinforce the pathologic mechanisms of galectin-3 and support its putative role in arrhythmogenesis and sudden cardiac death." (PMID 39338248, 2024).
cardiac interstitial fibrosis (4 papers, 2016 to 2022). "Taken together, galectin-3 might be strongly associated with cardiac remodeling and could predict patterns of geometric remodeling induced by cardiac interstitial fibrosis in dogs with heart diseases." (PMID 34722704, 2021).
cerebral infarction (4 papers, 2018 to 2026). An ischemic condition of the brain, producing a persistent focal neurological deficit in the area of distribution of the cerebral arteries. "However, available data suggest that elucidating the role of galectin-3 in EBI would provide new insight into the mechanisms of EBI, and a novel therapeutic approach for EBI or neuroinflammation to prevent delayed cerebral infarction and to improve outcomes after SAH." (PMID 29414883, 2018). "Although high plasma galectin-3 levels seem to correlate with the severity of SAH, subsequent development of delayed cerebral infarction without cerebral vasospasm, and poor outcomes, the functional role and molecular mechanisms of galectin-3 in SAH remain unclear." (PMID 29414883, 2018).
chordoma (4 papers, 2021 to 2025). Chordomas are rare malignant tumors arising from embryonic remnants of the notochord in axial skeleton. "In addition to the well‐known chordoma biomarkers (LGALS3 and TBXT), the heatmap also revealed IGKV2, IL13RA2, RAB3B, and MAPK3 highly expressed in chordoma." (PMID 40135815, 2025).
dry eye (4 papers, 2015 to 2024). "In the dry eye model proposed, an increased secretion of IL-1β was observed, as well as an upregulation of NF-κB, occludin and galectin-3 mRNA expression." (PMID 35562958, 2022). "LGALS3 cleavage products are found at the ocular surface and in tears of dry eye patients, and we provide evidence here that LGALS3 is cleaved at the mouse ocular surface subjected to desiccating stress." (PMID 26402857, 2015).
ductal adenocarcinoma (4 papers, 2016 to 2025). "Patients with a diagnosis of invasive ductal carcinoma at the time of sample retrieval had significantly elevated mean galectin-3 levels compared to patients with ductal carcinoma in situ histology." (PMID 38927753, 2024). "Based on these findings, a pooled t-test for differences in means was performed to compare mean serum galectin-1 levels between invasive ductal carcinoma and ductal carcinoma in situ, while a Welch’s t-test was performed for galectin-3 and -9." (PMID 38927753, 2024). "Patients with invasive ductal carcinoma had significantly higher serum galectin-3 levels than patients with ductal carcinoma in situ." (PMID 38927753, 2024). "Analysis of data from The Cancer Genome Atlas (TCGA) demonstrated that gene expression (LGALS3) decreases sequentially from normal tissue to ductal breast carcinoma in situ to invasive ductal breast carcinoma." (PMID 27687248, 2016). "A Levene’s Test for Homogeneity of Variance was performed, indicating a statistically significant difference in variances between the samples from patients with invasive ductal carcinoma and the samples from patients with ductal carcinoma in situ for galectin-3 and -9." (PMID 38927753, 2024).
ductal carcinoma in situ (4 papers, 2010 to 2024). "The ITRAQ data was confirmed by immunoblotting and is consistent with another study that described detectable expression of Galectin 3 in normal ducts and down-regulation in ductal carcinoma in situ." (PMID 20543960, 2010). "In an attempt to improve diagnostic accuracy, markers used for immunohistochemistry have been studied, such as galectin-3, HBME-1 and CK-19 for diagnosis of benign and malignant thyroid lesions, and FAP-α and Calponin for diagnosing whether ductal carcinoma in situ has microinvasion." (PMID 24502396, 2014).
frontotemporal dementia (4 papers, 2022 to 2025). Frontotemporal dementia (FTD) comprises a group of neurodegenerative disorders, characterized by progressive changes in behavior, executive dysfunction and language impairment, as a result of degeneration of the medial prefrontal and frontoinsular cortices. "Galectin-3 also accumulates in the brains of patients with AD and frontotemporal lobar degeneration." (PMID 39592224, 2024).
interstitial lung disease (4 papers, 2018 to 2025). A diverse group of lung diseases that affect the lung parenchyma. "Additionally, the elevation of LGALS3 in SS stages suggests its role as an alarmin, particularly in SS patients with interstitial lung disease, and underscores the intricate interplay between LGALS3, LCN2, SS, and TC." (PMID 39928612, 2025).
meningioma (4 papers, 2010 to 2023). A generally slow growing tumor attached to the dura mater. "One previous immunohistochemical study showed that fibronectin, galectin-3, matrix metalloproteinase 2, matrix metalloproteinase 9, and collagen IV were highly expressed in meningioma tissues." (PMID 36538194, 2022). "Similar biomarkers were also reported in 2014; the expression of galectin-3, vimentin was decreased significantly in meningiomas, and the expression of 40S ribosomal protein S12 and glutathione S-transferase was increased significantly." (PMID 32983987, 2020). "It is worth mentioning that the function of galectin-3 was further investigated in 2017; high expression of galectin-3 was observed in meningioma infiltration and recurrence." (PMID 32983987, 2020). "However, the role of galectin-3 in meningioma remains controversial; there is still a need for further studies to confirm the exact mechanism of galectin-3 in meningioma." (PMID 32983987, 2020).
oral squamous cell carcinoma (4 papers, 2017 to 2022). "Galectin-1 and galectin-3 are intriguing markers for oral squamous cell carcinoma for the screening of higher risk populations." (PMID 31832021, 2019). "The current study revealed an association between Galectin 3 (Gal3) expression in oral squamous cell carcinoma (oscc) tissue and histomorphologic parameters of tumor progression (T-, N-, L-, Pn-stage, grading)." (PMID 29284429, 2017). "In oral squamous cell carcinoma (OSCC), inhibition of Galectin-3 has been shown to overcome cetuximab‐resistance in murine animal models." (PMID 36289103, 2022).
peritonitis (4 papers, 2017 to 2023). Inflammation of the peritoneum (tissue that lines the abdominal wall and covers most of the organs in the abdomen). "Expression of galectin-3 by exudated neutrophils drives neutrophil apoptosis and clearance in a model of self-resolving peritonitis." (PMID 27733579, 2017). "In another animal study, intravenous injection of Gal-1, but not galectin-3, inhibited leukocyte recruitment into the peritoneal cavity in rats with experimental peritonitis." (PMID 34559847, 2021).
pituitary adenomas (4 papers, 2010 to 2021). "It has been demonstrated that the expression of Lgals3 (galectins) in pituitary adenomas is positively associated with the prolactin level in pituitary tumorigenesis." (PMID 32183190, 2020). "In the pituitary, galectin-3 is expressed in normal lactotroph and corticotroph cells, resulting in over-expressed pituitary adenomas and carcinomas." (PMID 34322092, 2021).
prostate intraepithelial neoplasia (4 papers, 2020 to 2025). A neoplastic proliferation of the epithelial cells that line the acini and the ducts of the prostate gland. "LGALS3, expressed in human prostate intraepithelial neoplasia lesions and metastatic lymph nodes, is a crucial molecule and a potential therapeutic target in PCa progression and metastasis." (PMID 36980585, 2023).
sarcopenia (4 papers, 2022 to 2026). Progressive decline in muscle mass due to aging which results in decreased functional capacity of muscles. "In addition to hsCRP, Kynurenine seems to be a reliable biomarker to monitor acute and regenerative inflammation status of alloSCT patients, while Musclin and Galectin-3 may be added to physiological assessment regarding myopathy and sarcopenia." (PMID 37256146, 2023). "Integrating mouse and human liver transcriptomics with muscle proteomics from MCD- and GAN-diet induced murine MASH models with sarcopenia, we identified three MASH-induced hepatokines, namely LCN2, LGALS3 and OPN." (PMID 42270040, 2026). "In other myopathies, ST identified Galectin-3–positive macrophages, GPNMB-expressing regenerative macrophages, and osteopontin/TGF-β signaling circuits as drivers of fibrosis or repair, offering translational insights into shared sarcopenia pathology." (PMID 40718353, 2025).